OCLN (occludin)
Diseases named in the same sentence as OCLN in open-access papers (continued):
Sharing a sentence is not in itself a finding about the gene and the disease.
periodontitis (10 papers, 2014 to 2026). An acute or chronic inflammatory process that affects the tissues that surround and support the teeth. "Compared with the control group, the expression of Occludin and ZO-1 protein was decreased in the brain of periodontitis mice, indicating that P. gingivalis infection led to BBB disruption." (PMID 40552124, 2025). "Firstly, periodontitis leads to the downregulation of tight junction proteins (e.g., ZO-1 and occludin) and increases gut permeability to facilitate mechanical barrier impairment." (PMID 40427685, 2025). "In the small intestine, experimental periodontitis significantly downregulated ZO-1 expression (P <0.05), and Claudin-1 and Occludin also showed less expression in experimental periodontitis mice." (PMID 35118014, 2021). "Strong reactivity for occludin was observed in external oral epithelia (OE) in both minimally inflamed gingiva (Min) and periodontitis (Perio) samples." (PMID 25866631, 2014). "In addition, HGF further significantly facilitated the downregulation of occludin in the context of periodontitis." (PMID 40427685, 2025). "HGF also diminished the protein level of occludin and upregulated NOD2 expression in mice with periodontitis." (PMID 40427685, 2025). "Very recent studies of Jiang and coworkers also found that in mice P. gingivalis-induced periodontitis enhanced BBB permeability, measured as Evans Blue leakage, and downregulated the expression of Occludin and ZO-1." (PMID 41310669, 2025). "P. gingivalis-induced periodontitis enhanced BBB permeability, promoted P. gingivalis and immune cell infiltration, and downregulated the expression of Occludin and ZO-1." (PMID 40552124, 2025). "The periodontitis-affected gingival epithelium highly expressed tight junction genes claudin-1 (CLDN1) and E-cadherin (CDH1) (p < 0.001), while the average expression of occludin (OCLN) was also elevated, although this was not statistically significant." (PMID 41358003, 2025). "Notably, we observed the selective downregulation of occludin but not ZO-1 in HGF-Tg mice, suggesting that HGF may preferentially target specific TJ components during periodontitis." (PMID 40427685, 2025).
pulmonary edema (10 papers, 2014 to 2025). Accumulation of fluid in the lung tissues causing disturbance of the gas exchange that may lead to respiratory failure. "Stimulation of mouse lungs with LPS can increase pulmonary microvascular permeability through a process associated with tight junction proteins such as Occludin, Claudin-5, and zonula occluden-1 (ZO-1), leading to pulmonary oedema in mice." (PMID 38802896, 2024). "Decreased expression of VE-cadherin, Occludin, Claudin-5, and ZO-1 can significantly increase endothelial permeability, cause pulmonary edema, and aggravate lung injury.VE-cadherin can further enhance tight junction formation by promoting the expression of Claudin-5." (PMID 30867053, 2019). "Second, J. regia L.'s hydroalcoholic extract resulted in the amelioration of pulmonary edema, which is attributed to the upregulation of HO-1, occludin, and ZO-1 in the lung tissues of J. regia L– treated groups when compared to the DC group." (PMID 40421046, 2025). "J. regia L.'s hydroalcoholic extract resulted in the amelioration of pulmonary edema, which is attributed to the upregulation of HO-1, occludin, and ZO-1 in the lung tissues of the J. regia L.–treated groups when compared to the DC group." (PMID 40421046, 2025). "Ulinastatin ameliorates pulmonary edema by upregulating the expression of ZO-1 and occludin, thereby reducing pulmonary permeability and stimulating alveolar fluid clearance." (PMID 38166725, 2024). "Mechanical stretch induced the degradation of tight junction proteins such as occludin, potentially leading to pulmonary edema; however, the degradation of occludin was decreased in EX + MV group, in which NLRP3 was downregulated by aerobic exercise." (PMID 36456896, 2022). "Juglans regia L.'s hydroalcoholic extract resulted in the amelioration of pulmonary edema which is attributed to the upregulation of HO-1, occludin, and ZO-1 in the lung tissues of the Juglans regia L. treated groups when compared to the diseased control group." (PMID 40421046, 2025). "Further, Solnatide (AP301), a specific direct activator of ENaC, was able to restore alveolar epithelial barrier function, including occludin expression, and reduce pulmonary edema in a rat model of high altitude pulmonary edema, showing the therapeutic potential of ENaC regulation." (PMID 34675326, 2021). "BBG administration decreased mature interleukin-1β, myeloperoxidase, and matrix metallopeptidase-9 activation, but increased tight junction proteins, such as ZO-1 and occludin, which ameliorated pulmonary edema via anti-inflammation and improved neurological deficits." (PMID 24533168, 2014). "However, the expression levels of VE-Cadherin, Occludin, Claudin-5, and ZO-1 were significantly increased after treatment with BMSCs, showing that BMSCs might reduce pulmonary edema by strengthening the adhesion and tight junction between cells." (PMID 30867053, 2019). "Thus, it is suggested that fasudil ameliorates LPS-evoked pulmonary edema by increasing the expression of AQP5 and occludin." (PMID 28963443, 2019).
Alzheimer disease (9 papers, 2015 to 2026). A progressive, neurodegenerative disease characterized by loss of function and death of nerve cells in several areas of the brain leading to loss of cognitive function such as memory and language. "Similarly to occludin, claudin-5 has been described to be susceptible to the action of MMPs, as it was observed in an in vitro model of Alzheimer’s disease." (PMID 32867861, 2020). "Altered expression of tight junction proteins have also been reported in Alzheimer’s disease, notably including reduced Occludin with increasing tau accumulation, which was also observed in this mouse model." (PMID 32811565, 2020). "Our results are consistent with those obtained in other brain injuries such as hypoxic/ischemic brain injury and Alzheimer’s disease, in which the tight junction proteins claudin-V, occludin, and ZO-1 have demonstrated a role as promising biomarkers for cerebrovascular dysfunction." (PMID 41596222, 2026).
endothelial dysfunction (9 papers, 2018 to 2025). In vascular diseases, endothelial dysfunction is a systemic pathological state of the endothelium (the inner lining of blood vessels) and can be broadly defined as an imbalance between vasodilating and vasoconstricting substances produced by (or acting on) the endothelium. "Accordingly, this study also examined tight junction proteins that are closely associated with endothelial dysfunction, including ZO-1, Occludin, and Claudin-5, and found that tight junction protein expression was essentially reduced in the SHRs injected with D-gal for 12 weeks." (PMID 40080509, 2025). "It has also been found that tight junction proteins are proteins that regulate the permeability of the epithelial and endothelial tissue barriers, including ZO-1, Occludin, Claudin-5 and are closely related to endothelial dysfunction." (PMID 40080509, 2025). "miR-142 regulates the expression of occludin, which affects endothelial permeability, contributing to endothelial dysfunction." (PMID 39311385, 2024). "In a recent study, we explored the role of autophagy during ischemic stress in brain ECs and showed that autophagy promotes endothelial dysfunction through occludin degradation." (PMID 32899154, 2020). "Specifically, this cluster of correlation has high levels of serum occludin, IL-6 receptor (IL-6R), soluble intercellular adhesion molecule-1 (sICAM-1) and vascular endothelial (VE)-cadherin, with potential inflammatory-induced endothelial dysfunction." (PMID 39182041, 2024). "Differently, the other cluster had high levels of serum occludin, IL-6R, soluble intercellular adhesion molecule-1 (sICAM-1) and VEC, with potential inflammatory-induced endothelial dysfunction." (PMID 39182041, 2024). "Consequentially, this response appears to contribute to endothelial dysfunction within the NVU, with reduced expression of key tight junction elements Zonula Occludens-1 and Occludin up to 3 days post-TBI." (PMID 29618365, 2018). "Understanding the dysfunction and non-canonical roles of claudin-5 and occludin provides valuable perspectives for exploring therapeutic strategies targeting endothelial dysfunction in AVM pathology." (PMID 40429705, 2025).
Hepatic steatosis (9 papers, 2013 to 2025). Steatosis is a term used to denote lipid accumulation within hepatocytes. "Oral coffee acid, a kind of antioxidant (60 mg/kg body weight), could increase the expression of ZO-1 and Occludin against a high-fat diet (HFD)-induced hepatic steatosis and inflammation." (PMID 36406080, 2022). "Meanwhile, oral CGA (60 mg/kg body weight) also could increase the expression of ZO-1 and Occludin against high-fat diet (HFD)-induced hepatic steatosis and inflammation." (PMID 34867926, 2021). "I3C treatment reduces body weight, hepatic steatosis, and systemic inflammation of HFD-fed mice, ameliorates insulin resistance, and significantly augments the expression of Claudin4, Occludin, and ZO-1 to enhance intestinal barrier protein function." (PMID 39830328, 2024). "Similarly, models of fatty liver disease, e.g. induced by dietary fructose or by lack of leptin showed that occludin protein expression is decreased and portal endotoxin levels are elevated in the small intestine." (PMID 24321090, 2013).
liver fibrosis (9 papers, 2012 to 2024). "UA supplementation increased the expression of claudin-1 and occludin in the ileum of rats with CCl4-induced hepatic fibrosis." (PMID 39272277, 2024). "After rats with liver fibrosis were exposed to chronic psychological stress, occludin protein expression was further reduced compared with rats with liver fibrosis and those with chronic psychological stress (p < 0.001)." (PMID 36579341, 2022). "Western blot analysis was conducted to determine the protein expression of liver fibrosis (HA and LN)– and intestinal mucosal barrier function–related proteins (occludin and ZO‐1) in liver tissues and small intestine tissues, respectively." (PMID 32324317, 2020). "We found that the expression of occludin and claudin-1 in the rat intestinal tract decreased significantly in CCl4-induced liver fibrosis rats, while DOP enhanced the expression of these proteins." (PMID 32226380, 2020). "After QJ, the intestinal tissue structure of mice returned to normal, the expression levels of Claudin-1, Occludin and ZO-1 increased, the TJ apparatus damaged by CCl4 was restored, and liver inflammation and liver fibrosis were inhibited by repairing the intestinal epithelial barrier." (PMID 39234554, 2024). "In human liver samples obtained from three patients without liver fibrosis and three patients with liver fibrosis, the bile canaliculi of hepatocytes were strongly positive for occludin while the liver sinusoids were not stained with anti-occludin antibodies." (PMID 22509281, 2012). "Occludin protein was abundantly expressed in intestinal tissue of normal rats, and its expression was significantly decreased in both the stress group (p = 0.047) and the liver fibrosis group (p = 0.035), but there was not statistically different between both groups (p = 0.31)." (PMID 36579341, 2022).
multiple sclerosis (9 papers, 2012 to 2025). A progressive autoimmune disorder affecting the central nervous system resulting in demyelination. "In the white matter of humans with multiple sclerosis, tight junction disruption (ZO-1 and occludin) has been shown to lead to BBB leakage." (PMID 32344633, 2020). "Similarly, clinical data also showed that astrocyte-derived Ang II stabilizes BBB permeability by threonine-phosphorylation of occludin in patients with multiple sclerosis." (PMID 27199659, 2016). "In experimental autoimmune encephalomyelitis, a well-characterized model of multiple sclerosis changes in claudin-5 immunostaining in brain vessels were evident at a very early disease stage, while the initially preserved occludin pattern showed alterations at more advanced stages." (PMID 26834555, 2015).
Salmonella Infections (9 papers, 2018 to 2024). Infections with bacteria of the genus SALMONELLA. "In the current experiment, dietary AC alleviated the adverse effects of chickens caused by Salmonella infection by up-regulating expression of ZO-1, claudin-1, occludin, and MUC2." (PMID 36670458, 2023). "By analogy, Salmonella infection also reduced the expression of the OCLN and CLDN1 genes in the ileum and jejunum of broiler chickens and reduced the intestinal barrier function." (PMID 39682509, 2024). "Previous studies showed that Salmonella infection induced intestinal barrier injury by suppressing gene expression of tight junction proteins (ZO-1, claudin-1 and occludin) and MUC2." (PMID 36670458, 2023). "Previous studies have shown that Salmonella infection led to intestinal damage, increased permeability and downregulated the expression of Occludin and Claudin in mice." (PMID 37893938, 2023). "Salmonella infection has been observed to down-regulate the expression of Occludin and ZO-1 genes in the jejunum, as well as Occludin and Claudin genes in the ileum." (PMID 37835714, 2023). "Our results showed that Salmonella infection down-regulated the gene expression of Occludin and Claudin in the ileum and jejunum of broiler chickens." (PMID 32054193, 2020). "Salmonella infection downregulated gene expression of Occludin, zonula occludens-1 (ZO1), and Mucin 2 in the jejunum and Occludin and Claudin in the ileum." (PMID 32054193, 2020). "The tight junction, composed of claudin, occludin, and zonula occludens (ZO)-1, has been shown previously to protect against Salmonella infection." (PMID 29456533, 2018). "In the ileum, Salmonella infection significantly reduced Occludin (p<0.001) and Claudin (p = 0.022) gene expression, and probiotic supplementation significantly increased the mRNA expression of Occludin (p<0.001), ZO1 (p = 0.005), Mucin 2 (p<0.001), and Claudin (p = 0.051)." (PMID 32054193, 2020). "Additional observations indicated that mice were more resistant to Salmonella infection and disruption of gut barrier permeability when ß-catenin expression was modified to be constitutively active in intestinal endothelial cells, altering occludin and ZO-1 expression." (PMID 35976519, 2023). "In contrast, Salmonella infection seemingly showed the opposite trend for occludin mRNA expression, but without any statistical differences between the infected and non-infected groups in the ileum." (PMID 33670419, 2021).
type 2 diabetes (9 papers, 2012 to 2025). "Occludin was unexpectedly increased in the parietal cortex of individuals with type 2 diabetes." (PMID 37351595, 2023). "Peanut skin procyanidins, including B1 and B2 forms, offered to type 2 diabetic mice preserved villus length and crypt depth, improved the gut barrier integrity by enhancing colon tight junction protein expression including zonula occludens-1, claudin-1 and occludin." (PMID 39980683, 2025). "Further studies measuring various parameters of gut integrity, such as occludin, claudins, or mucin, in addition to LBP and zonulin, are necessary to determine the impact of brown seaweed and their extracts on gut integrity among people at risk of type 2 diabetes." (PMID 35323474, 2022).
brain injury (8 papers, 2013 to 2024). Acute and chronic (see also brain INJURIES, CHRONIC) injuries to the brain, including the cerebral hemispheres, CEREBELLUM, and brain STEM. "mRNA transcription and protein expression of TJ-associated proteins (claudin-5, occludin, and ZO-1) are significantly reduced following traumatic brain injury, and these changes are consistent with greater BBB permeability." (PMID 26290681, 2015). "Isolation and analysis of eMVs from blood plasma using cryo-EM and flow cytometry revealed elevated levels of vesicles containing occludin following brain trauma." (PMID 26973460, 2016). "Levels of circulating claudin-5 and occludin are increased after hypoxic/ischemic brain injuries and blood–brain barrier-impairment and have promise as early biomarkers for cerebral vascular dysfunction and as a tool for risk assessment of neonatal brain injuries." (PMID 33568200, 2021). "Taken together, these findings indicate that Shuanghe-tang pretreatment may attenuate BBB dysfunction and edema following ischemic brain injury by promoting increased expression of ZO-1, occludin, and AQP4." (PMID 29599893, 2018). "In a murine model of traumatic brain injury (TBI) or severe burn injury, increases in intestinal barrier failure, as evidenced by increased paracellular permeability and histologic gut injury, were associated with decreased expression or altered localization of both occludin and ZO-1." (PMID 23840906, 2013). "Our findings demonstrate that HGD intervention effectively restored the reduced expression of Claudin-5, Occludin, and ZO-1 induced by alcohol exposure, suggesting that HGD may enhance the structural integrity of the BBB in rats with alcohol-induced brain injury." (PMID 39229571, 2024).
Constipation (8 papers, 2022 to 2025). Infrequent or difficult evacuation of feces. "The expression levels of Occludin were higher only in the AELP-treated Lop-induced constipation model, while the levels were maintained constant in other groups." (PMID 41011160, 2025). "The authors further investigated the effects of ECAE and HDAE on the expression levels of three intestinal tight junction proteins, Zonula Occludens-1 (ZO-l), Occludin and Claudin-l, in the colonic tissues of constipation model mice." (PMID 40432966, 2025). "The water extract of Cannabis sativa L. was found to significantly reverse the reduction in the expression of gut barrier-related molecules, including Claudin-1 and Occludin, at the mRNA level in constipation model mice." (PMID 40432966, 2025). "The expression levels of three TJ components, including occludin, ZO-1, and claudin-1, except claudin-4, were significantly recovered in the Lop-induced constipation rat model after treatment with phlorotannin (Pt)." (PMID 39857371, 2024). "Also, other changes, such as increased ZO-1, decreased claudin-1, and no change in occludin, were detected in Lop-induced constipation mice after treatment with Wenyang Yiqi Decoction (WYD)." (PMID 39857371, 2024).
gastric cancer (8 papers, 2002 to 2026). A primary or metastatic malignant neoplasm involving the stomach. "RRAD inhibition could also suppress expression of EMT-associated proteins (VIMENTIN, TWIST, SNAIL, and OCCLUDIN), VEGF, and ANGP2 in gastric cancer (GC) and colorectal cancer (CRC) cell lines." (PMID 36979412, 2023). "However, to our knowledge, no other reports related to galectin 3, S100A10, desmoplakin, occludin, keratins 8, 14, myosin VI, tubulin beta 4 and calveolin-3 in gastric cancer have been published." (PMID 12402156, 2002). "MICAL-L2 has been reported to mediate the endocytic recycling of occludin, while we have also recently shown that MICAL-L2 promotes the migration of gastric cancer cells via inhibiting EGFR transportation and degradation." (PMID 35501725, 2022). "Interrogation of CCLE database revealed that FZD5 is positively correlated with epithelial-related factors CDH1 (E-cadherin), OCLN (Occludin), EPCAM and ELF3, while negatively correlated with mesenchymal-related factors VIM (Vimentin), SNAI2 (Slug), ZEB1 and ZEB2 in 37 gastric cancer cell lines." (PMID 33618713, 2021).